JAK2 (Janus kinase 2)
Diseases named in the same sentence as JAK2 in open-access papers (continued):
Sharing a sentence is not in itself a finding about the gene and the disease.
ischemia reperfusion injury (3 papers, 2020 to 2023). Adverse functional, metabolic, or structural changes in ischemic tissues resulting from the restoration of blood flow to the tissue (reperfusion), including swelling; hemorrhage; necrosis; and damage from free radicals. "The study aims to investigate the effect of JAK2 signaling on the expression of the Keap1/Nrf2 axis, spermatogenesis, and the Sertoli cells (Sc) junctions in an animal model of testicular ischemia reperfusion injury (tIRI)." (PMID 37759514, 2023). "The JAK2/STAT3 signaling pathway is involved in the expression of a large number of cytokines, growth factors, and hormones and also plays a crucial role in protecting the myocardium from an ischemia-reperfusion injury." (PMID 35281544, 2022).
laryngeal carcinoma (3 papers, 2019 to 2023). Carcinoma that arises from the laryngeal epithelium. "Brusatol reversed the Hep-2 cell epithelial-mesenchymal transition (EMT) process, abolishing the Janus kinase 2 (JAK2)/STAT3 signaling pathway in laryngeal cancer cell line." (PMID 38371913, 2023). "STAT3 mediates angiogenesis in laryngeal cancer, and inhibition of the JAK-2/Stat-3 signaling pathway significantly inhibits invasion in vitro and angiogenesis of laryngeal cancer." (PMID 33344242, 2020). "The results revealed that SOX18 promoted carcinogenesis in laryngeal carcinoma via activating JAK2/STAT3 signaling." (PMID 31189744, 2019). "JAK2/STAT3 signal pathway exists in various types of cancers including laryngeal cancer, which is correlated with cell proliferation, apoptosis, and differentiation." (PMID 31189744, 2019). "Overexpression of SOX18 was found in the tumor tissues of laryngeal carcinoma patients, which regulated cell proliferation, migration, and invasion of laryngeal carcinoma cells through JAK2/STAT3 signaling." (PMID 31189744, 2019). "Consequently, we demonstrated that SOX18 was overexpressed in laryngeal carcinoma cell lines and tissues, and regulated the cell proliferation, cell cycle, apoptosis, migration, and invasion of laryngeal carcinoma cells via JAK2/STAT3 signaling." (PMID 31189744, 2019). "In addition, it was found that SOX18 could also accelerate the phosphorylation of JAK2/STAT3 signaling in laryngeal carcinoma cells." (PMID 31189744, 2019). "Furthermore, our study indicated that SOX18 could stimulate cell proliferation, migration, and invasion of laryngeal carcinoma cells via regulation of JAK2/STAT3 signaling, which could provide a new strategy for laryngeal carcinoma diagnosis and molecular therapies." (PMID 31189744, 2019).
lipid metabolism disorders (3 papers, 2011 to 2025). "In conclusion, the present study appears to describe for the first time significant associations of common variants in JAK2 gene with MS and lipid metabolism disorders, such as HW, TG/HDL-C and LAP." (PMID 22185674, 2011). "Targeting JAK-2/STAT-3 has also been reported to be beneficial for the treatment of lipid metabolism disorders." (PMID 40474319, 2025). "Thus, we hypothesize that COE may elevate leptin expression to activate OB-Rb, which subsequently induces increased phosphorylation of the JAK2/STAT3 pathway involved in hepatic inflammation and lipid metabolism disorder." (PMID 36539694, 2022).
lymph node metastasis (3 papers, 2018 to 2022). "Poor TNM stages and lymph node metastases were associated with higher levels of IL-6, p-JAK2, JAK2, p-STAT3, and STAT3 in patients with NPC." (PMID 36313702, 2022). "The expressions of IL-6, STAT3, p-STAT3, JAK2, p-JAK2 and CyclinD1 in NPC tissues were higher and correlated with TNM stage and lymph node metastasis (LNM)." (PMID 34165442, 2021).
male infertility (3 papers, 2023 to 2025). The inability of the male to effect fertilization of an ovum after a specified period of unprotected intercourse. "In fact, a lower expression of JAK2 mRNA and high expression of miR-135a-5p (a micro-RNA able to inhibits JAK2 expression) were related to asthenozoospermia and male infertility." (PMID 38900205, 2024). "The results emphasized the regulatory role of JAK2/STAT3, NLRP3/Caspase-1 signaling in testicular tissue maintenance to resist PbAc-induced dysfunctions and male infertility." (PMID 40356721, 2025). "The results further emphasized the regulatory role of JAK2/STAT3 on spermatogenesis, Keap1/Nrf2 signaling, and maintenance of the testicular redox balance to combat testicular dysfunction and male infertility." (PMID 37759514, 2023).
malignant glioma (3 papers, 2018 to 2022). A grade III or grade IV glioma arising from the central nervous system. "A phase I clinical trial (NCT01904123) with the JAK2 inhibitor WP1066 in patients with recurrent malignant glioma is ongoing." (PMID 35562901, 2022). "However, the ability of RXFP1 to engage the JAK3‐STAT3 signaling pathway provides a hitherto underappreciated new route of promoting GBM invasiveness and, in part, may explain the limited treatment success of JAK2 inhibitors in malignant glioma." (PMID 33960104, 2022).
mycosis fungoides (3 papers, 2013 to 2022). Classical mycosis fungoides is the most common type of mycosis fungoides (MF), a form of cutaneous T-cell lymphoma, and is characterized by slow progression from patches to more infiltrated plaques and eventually to tumors. "Interphase FISH excluded JAK2 translocations in 217 PTCLs from 200 patients with: angioimmunoblastic TCL: 60; ALCL, 53 (15 ALK-positive, 23 ALK-negative, and 15 cutaneous); PTCL-not otherwise specified, 59; extranodal NK/TCL, 11; mycosis fungoides, 5; and other cytotoxic PTCLs." (PMID 23372669, 2013).
Myelodysplasia (3 papers, 2019 to 2022). Clonal hematopoietic stem cell disorders characterized by dysplasia (ineffective production) in one or more hematopoietic cell lineages, leading to anemia and cytopenia. "Mutations that are rare in solid tumors such as JAK2 V617F can be assumed to be non-tumor derived and their presence may even be a reason for clinical follow-up and monitoring for development of myelodysplasia." (PMID 36470901, 2022).
myeloid sarcoma (3 papers, 2014 to 2021). A tumor mass composed of myeloblasts or immature myeloid cells. "In this report, we describe a series of clonal events in an elderly patient originally diagnosed with JAK2 V617F-positive ET who presented in accelerated phase, with subsequent progression to concurrent myeloid sarcoma (MS) and B-cell ALL." (PMID 34022887, 2021).
myocarditis (3 papers, 2024 to 2025). Myocarditis is a condition that is characterized by inflammation of the heart muscle (myocardium). "Ongoing research into myocarditis has targeted the same pathway but with JAK2 inhibitors and/or abatacept." (PMID 40647363, 2025).
neuroblastoma (3 papers, 2013 to 2024). Neuroblastoma (NB) is the most common solid, extracranial childhood tumor. "Our findings revealed that both agents individually and synergistically inhibit the activation of Jak2 and subsequent phosphorylation of Stat3, a critical transcription factor involved in promoting cell survival and proliferation in neuroblastoma." (PMID 39356934, 2024). "NP, which can inactivate Jak2/Stat3, can be used as a treatment agent by combining with DX in proliferation pathway in neuroblastoma." (PMID 39356934, 2024). "In the scope of the study, vehicle control, DX and NP doses were applied individually and in combination to SH-SY5Y neuroblastoma cells, and IL-6, IL-6-R, Jak2, and Stat3 gene expressions were determined at the end of 48 hours." (PMID 39356934, 2024). "In this study, we demonstrated that NP and DX effectively suppress the proliferation of neuroblastoma cells by targeting the Jak2/Stat3 signaling pathway." (PMID 39356934, 2024). "This suppression of the Jak2/Stat3 pathway resulted in significant growth inhibition and increased apoptosis in neuroblastoma cells." (PMID 39356934, 2024). "The aim of this study was to investigate the effects of napabucasin and doxorubicin on suppressing the proliferation of neuroblastoma cells through the Jak2/Stat3 signaling pathway." (PMID 39356934, 2024). "Our results suggested that the combined use of NP and DX could be a promising therapeutic strategy for targeting the Jak2/Stat3 pathway in neuroblastoma, offering a potential avenue for enhancing effective treatment and overcoming resistance to conventional therapies." (PMID 39356934, 2024). "We showed that NP prevents the invasion and proliferation of neuroblastoma SH-SY5Y cells and that this effect is achieved by suppressing Jak2/Stat3 signaling pathway." (PMID 39356934, 2024). "In neuroblastoma, mesenchymal stromal cells activate the MEK/ERK1/2 axis that induces—together with the Janus kinase 2 (JAK2)/STAT3 pathway—resistance to etoposide." (PMID 31117237, 2019).
neuropathy (3 papers, 2023 to 2025). A disorder affecting the nervous system that manifests with pain, tingling, numbness, and/or muscle weakness. "In order to further confirm the involvement of Janus kinase 2 (JAK2) downstream of the CXCR2 pathway in the development of oxaliplatin-induced neuropathy, ruxolitinib, a JAK2 inhibitor, was administered to the oxaliplatin-treated mice (n = 5)." (PMID 36768178, 2023).
periodontitis (3 papers, 2023 to 2024). An acute or chronic inflammatory process that affects the tissues that surround and support the teeth. "In addition, mandibular BM-MSCs from periodontitis mice also showed markedly more activated JAK/STAT3 signaling, as evidenced by higher levels of JAK2 and phosphorylated STAT3 proteins." (PMID 37490712, 2023).
pituitary adenoma (3 papers, 2017 to 2025). "JAK2/STAT5B pathway was identified as a key biological event in ER-mediated growth of pituitary adenoma." (PMID 36605480, 2023). "Interestingly, IL6R signaling through the JAK2/STAT3/MMP9 axis was previously reported to promote the invasion of pituitary adenoma cells." (PMID 40002253, 2025). "Both AZD9496 and fulvestrant could significantly block JAK2/STAT5B pathway in pituitary adenoma models." (PMID 36605480, 2023).
plaque psoriasis (3 papers, 2021 to 2025). "IL-23 dominates in plaque psoriasis and plays a major role in modulating JAK2/TYK2 and STAT signaling, thereby increasing IL-17 production by immune cells." (PMID 40920623, 2025). "This has led to FDA approval of topical ruxolitinib (marketed as JAK1- and JAK2-selective) and oral preparations of abrocitinib and upadacitinib (both JAK1-selective) for AD, as well as oral deucravacitinib (TYK2-selective) for plaque psoriasis." (PMID 37298195, 2023). "Oral tofacitinib, is a JAK1 and JAK2 inhibitor and is the most studied oral JAK inhibitor in moderate to severe plaque psoriasis." (PMID 34884596, 2021).
polycystic ovary syndrome (3 papers, 2015 to 2020). A disorder that manifests as multiple cysts on the ovaries. "For instance, total flavonoids regulated serum levels of FSH, luteinizing hormone (LH), and testosterone (T) in polycystic ovary syndrome rats by inhibiting the JAK2/STAT3 pathway." (PMID 32477106, 2020).
pyoderma gangrenosum (3 papers, 2016 to 2025). An idiopathic, rapidly evolving, and severely debilitating disease occurring most commonly in association with chronic ulcerative colitis. "Tan and Tolkachjov (2024) reported that pyoderma gangrenosum lesions exhibit elevated levels of proinflammatory molecules, including various cytokines, interleukins, JAK-1, JAK-2, JAK-3, and interferon gamma." (PMID 40353091, 2025).
silicosis (3 papers, 2023 to 2025). Silicosis is a respiratory disease caused by breathing in (inhaling) silica dust. "Our findings clearly support the theory that BIC reduces inflammation in silicosis via inhibitory effects on the JAK2/STAT3/SOCS3 signaling pathway." (PMID 39060930, 2024). "It has recently been identified as a promising anti-fibrotic agent against liver and pancreatic fibrosis through altering the TGF-β/Smad pathway and able to inhibit JAK2/STAT signaling pathway in a silicosis mouse model to reduce inflammatory cell infiltration and collagen deposition." (PMID 41293246, 2025). "Consistently, abnormally activated JAK2 and STAT3 as well as aberrantly expressed SOCS3 in lung tissues of silicosis rats were downregulated by BIC in the silicosis model." (PMID 39060930, 2024). "JAK2 and STAT3, crucial proteins in the JAK/STAT signaling pathway, play a significant role in regulating macrophage polarization in silicosis; inhibiting the expression of these proteins can delay the progression of silicosis." (PMID 37381044, 2023). "Similarly, in our silicosis model, both JAK2 and STAT3 were activated by TGF-β1 in fibroblasts, but not the other three cytokines, leading to promotion of the FMT process and wound healing." (PMID 39060930, 2024). "Hence, inactivation of JAK2/STAT3 signaling in macrophages may not be the only mechanism by which BIC reduces inflammation during silicosis." (PMID 39060930, 2024).
systemic sclerosis (3 papers, 2018 to 2024). A chronic disorder, possibly autoimmune, marked by excessive production of collagen which results in hardening and thickening of body tissues. "Other studies in human fibroblasts and mouse models of systemic sclerosis describe JAK2 activation by TGF-β1, which in turn phosphorylates STAT3 and leads to its nuclear translocation." (PMID 34207510, 2021). "Overexpression of p-JAK2 has also been reported in the cytoplasm of skin fibroblasts from systemic sclerosis (SSc) patients." (PMID 29409529, 2018). "The same signaling is observed in systemic sclerosis (SS), where TGF-β1 induces JAK2 phosphorylation, which then interacts with phosphorylated STAT3 to induce fibrotic responses." (PMID 34207510, 2021).
thoracic aortic aneurysm (3 papers, 2023 to 2026). An aneurysm formed in the wall of the proximal portion of the descending aorta proceeding from the arch of the aorta. "Search terms included "thoracic aortic aneurysm", "somatic mutations" and "JAK2 V617F"." (PMID 42074482, 2026). "However, recent research has identified a correlation between the JAK2 V617F somatic mutation and thoracic aortic aneurysm formation." (PMID 42074482, 2026). "Therefore, the presence of a small positive effect size for thoracic aortic aneurysms, alongside our findings in the internal database, supports further investigation into the role of the JAK2 V617F somatic variant in aortic disease." (PMID 39062663, 2024). "In our database of 12,439 exomes, 594 (4.8%) were found to have a thoracic aortic aneurysm (TAA), and 12 (0.049%) were found to have a JAK2 V617F variant." (PMID 39062663, 2024). "We also observed an increased prevalence of thoracic aortic aneurysms in the UKBB and FinnGen data among carriers of the JAK2 V617F variant (effect size 0.004)." (PMID 39062663, 2024). "In the case of JAK2 V617F, the somatic variant may not directly cause thoracic aortic aneurysms but could contribute to conditions that predispose individuals to this disease." (PMID 39062663, 2024).
thrombocythemia 3 (3 papers, 2018 to 2021). Familial thrombocytosis in which the cause of the disease is a mutation in the JAK2 gene. "In addition, germline variants in the JAK2 gene are causative for thrombocythemia 3 (OMIM ID: 614521); and in several cases, germline JAK2 variants, also in combination with other variants, were responsible for the activation of JAK2/STAT signaling in hereditary erythrocytosis or PV patients." (PMID 34349782, 2021).
tongue cancer (3 papers, 2016 to 2021). A malignant neoplasm affecting the tongue. "Therefore, we suggest that inhibited expression of genes involved in JAK2/STAT3 and MAPK signaling pathways might be related to the anticancer activities of DMU-214 and Gef in tongue cancer cells." (PMID 34201116, 2021). "The activation of the PI3 K/AKT and JAK2/STAT3 signaling pathways could promote the secretion of VEGF-C in cancer cells, suggesting that IER3 might induce the generation of VEGF-C in tongue cancer cells, but the specific molecular mechanism needs to be identified in further studies." (PMID 31832020, 2019).
transient ischemic attack (3 papers, 2021 to 2025). A brief attack (from a few minutes to an hour) of cerebral dysfunction of vascular origin, with no persistent neurological deficit. "In particular, activation of the JAK2/STAT3 signaling pathway may contribute to neuronal damage following transient cerebral ischemia in rats." (PMID 33514001, 2021).
zoster (3 papers, 2022 to 2025). "Baricitinib is also linked to a higher incidence of adverse events, particularly herpes zoster, due to its inhibition profile targeting JAK1 and JAK2." (PMID 39610670, 2024).
acquired von willebrand syndrome (2 papers, 2021 to 2025). "Symptomatic children or those with additional risk factors such as presence of JAK2-V617F may benefit from therapy with low-dose ASA along with careful monitoring while keeping in mind the risk of acquired von Willebrand syndrome and potentially Reye syndrome." (PMID 33712866, 2021). "Further investigations confirmed Janus kinase 2 (JAK2) mutation-positive ET and acquired von Willebrand syndrome (AvWS)." (PMID 41589191, 2025).
acute coronary syndrome (2 papers, 2024 to 2025). Signs and symptoms related to acute ischemia of the myocardium secondary to coronary artery disease. "Thus, excessive platelet number from Jak2 deficiency may lead to increased atherosclerotic risk as shown by increased CVD and acute coronary syndromes." (PMID 40825505, 2025).
acute erythroid leukemia (2 papers, 2015 to 2024). An acute myeloid leukemia characterized by a predominant immature erythroid population. "For this, human acute erythroid leukemia HEL cells, which naturally harbor the JAK2 V617F mutation homozygously, were treated for 4 h with DMSO or ruxolitinib and then incubated with and without the antimitotic drug NMS-P715 (MPS1i) to induce SAC malfunction." (PMID 38308077, 2024). "We defined the mechanisms through which Stat5 affects growth and survival of K562 cells, representative of Bcr-Abl positive CML, and HEL cells, representative for Jak2(V617F) positive acute erythroid leukemia." (PMID 25809097, 2015).
adenoma (2 papers, 2014 to 2025). A neoplasm arising from the epithelium. "In addition, in nonfunctioning adenomas, interleukin 6 receptor (IL-6R)/Janus kinase 2 (JAK2)/STAT3/matrix metallopeptidase 9 (MMP9) and phosphatidylinositol 3-kinases (PI3K) have been discovered to be involved in the PI3K/AKT pathway." (PMID 40299639, 2025).
Allergic Conjunctivitis (2 papers, 2023 to 2025). "Gp130 can promote allergic conjunctivitis by increasing the phosphorylation levels of JAK2 and STAT3." (PMID 40005151, 2025).
astrocytoma (2 papers, 2013 to 2022). "In our previously study, we had ever detected the expressions of JAK2 and pJAK2Tyr1007/Tyr1008, STAT3’s upstream, in the normal cortex and human astrocytoma tissues using immunohistochemistry." (PMID 24386409, 2013).
autism (2 papers, 2020 to 2024). Persistent deficits in social interaction and communication and interaction as well as a markedly restricted repertoire of activity and interest as well as repetitive patterns of behavior. "Activation of JAK2 in cases of autism induces phosphorylation of STAT3 in the astrocytes and microglia which in turn elicits profound damage to the neural tissues." (PMID 39596986, 2024). "Accumulating data suggested that Janus kinase 2 (JAK2)/signal transducer and activator of transcription-3 (STAT 3)/peroxisome proliferator-activated receptor (PPAR) gamma signaling pathway might play a pivotal role in the pathogenesis of autism." (PMID 39596986, 2024). "Furthermore, the JAK2 gene was found to have the highest expression level in the CBC, playing a central role in cognitive and emotional processing, which are key deficits in autism and other neuropsychiatric disorders." (PMID 31838722, 2020).
autism spectrum disorder (2 papers, 2020 to 2024). A spectrum of developmental disorders that includes autism, and Asperger syndrome. "Accumulating evidence highlighted the role played by the JAK2/STAT3 axis and PPAR-gamma signaling in the pathogenesis of autism spectrum disorders." (PMID 39596986, 2024).